INS (insulin)
Diseases named in the same sentence as INS in open-access papers (continued):
Sharing a sentence is not in itself a finding about the gene and the disease.
cancer (continued). "Enhanced understanding of molecular mechanisms regulating insulin signaling could inform the development of potential therapeutic strategies for cancer prevention." (PMID 37250804, 2023). "As fasting Insulin levels were constant in our IG and CG (−2.3 pmol/L vs. −1.1 pmol/L; p = 0.91), we cannot confirm study findings that proved training's positive effect on fasting Insulin in cancer patients." (PMID 37794972, 2023). "The oncogenic effect of insulin could be due to the overexpression of insulin receptor by cancer cells, but also to its ability to interact with the IGF1 receptor, especially at supraphysiologic doses and with the use of long-acting analogues." (PMID 38146457, 2023). "There are also differences in insulin sensitivity between cancer patients with or without associated cachexia, due to hormonal imbalances (vitamin D, testosterone, GLP-1, glucagon, ghrelin, apelin) and adipose tissue modifications." (PMID 38067294, 2023). "In addition to its well-established role in reducing persistently high plasma glucose and insulin levels, metformin stands out as a promising candidate for the prevention and treatment of malignant tumors." (PMID 38057926, 2023). "Despite these limitations, the study provides valuable insights into the potential targets and mechanisms of PPIs that exhibit dual effects of anti-cancer and hypoglycemic and highlights the importance of fatty acid transport and insulin resistance in these effects." (PMID 37165049, 2023). "Therefore, maintaining insulin sensitivity is crucial to prevent muscle wasting in patients with cancer cachexia." (PMID 37217930, 2023). "This evolutionary conserved control of cell proliferation and growth promoting factors by insulin signaling might also be of particular relevance to explain the fact that cancer’s vulnerability to food availability is a conserved trait." (PMID 37963956, 2023). "Furthermore, we did not see any benefit in survival for diabetic pts treated on an insulin-based or an insulin-free antidiabetic regimen at the time of initial cancer diagnosis." (PMID 37297851, 2023). "Moreover, inflammation can play a dominant role in deregulated signaling of the insulin/insulin-like growth factor system (IGFs) in obesity, diabetes, and cancer." (PMID 37884933, 2023). "This cancer-promoting effect may be mediated by systemic effects of insulin/insulin-related growth factor-1 (IGF-1) and inflammatory signaling." (PMID 37346909, 2023). "Nonetheless, in addition to typical markers of metabolic health, such as insulin regulation, waist circumference, and BMI, body metabolic rate (BMR), which reflects whole-body energy metabolism, has also been proposed as a relevant risk factor for cancer." (PMID 36834334, 2023). "Insulin promotes mitogenic and growth-stimulating effects in the prostate, all of which may contribute to the development of cancer." (PMID 37953784, 2023). "In these inflammatory pathological conditions, the multiligand receptor for advanced glycation end-products (RAGEs) is driven by aberrant cross-communication with the impairment of insulin/IGFs in modulating the gene transcription and protein translation in cancer." (PMID 37884933, 2023). "Lower systemic glucose and insulin levels by metformin use might decrease insulin-mediated tumor growth and progression in cancer." (PMID 37278858, 2023). "Studies have shown that cancer is more frequent in diabetic patients versus non-diabetic ones and more frequent in those treated with insulin (either in monotherapy or in association with oral antidiabetic drugs)." (PMID 36830690, 2023). "Clinical studies on KD in EOC, including a randomized clinical trial that compared patients on a KD to the standard American Cancer Society diet, showed that patients on a KD had improved insulin sensitivity, more favorable body composition, and decreased food cravings." (PMID 37375634, 2023).
cancer (continued). "Likewise, a phase 2 clinical trial with the first-generation TKI Imatinib conducted in non-cancer patients with recent-onset type 1 diabetes demonstrated an improvement in β-cell function and peripheral insulin sensitivity." (PMID 37592236, 2023). "However, other factors, such as how cancer treatments affect body composition, plasma lipids, or insulin sensitivity, should also be considered." (PMID 35748065, 2023). "In addition, by lowering glucose, levels of insulin and insulin-like growth factor, which are important drivers of cancer cell proliferation, are reduced." (PMID 37035188, 2023). "IR-B is mainly expressed in the major insulin target tissues, whereas IR-A is predominantly expressed in the embryo and fetal tissues, central nervous system (CNS), hematopoietic cells, and several types of cancer cells." (PMID 36975518, 2023). "PA may mediate numerous pathways involved in cancer progression and the development of other chronic diseases, including energy metabolism, insulin, chronic inflammation, the immune system, and antioxidant pathways." (PMID 37317668, 2023). "Proteins belonging to the insulin/IGF-1 pathway are also deregulated in cancer." (PMID 37895144, 2023). "Smoking and alcohol consumption do not statistically affect the incidence of this type of cancer, while a positive family history of cancer and diabetes (especially treated with insulin) significantly increases the risk of the disease." (PMID 37047829, 2023). "The reduction in oestrogen-sensitive cancers is consistent with other systematic reviews and is most likely related to the reduction in aromatase activity, plasma and tissue oestrogen and serum leptin and insulin following bariatric surgery." (PMID 37047163, 2023). "It is considered a key mediator of the beneficial effects of caloric restriction, exerts tumor suppressor activity in cancer and age-related disorders, regulates insulin secretion and signaling, improves aerobic metabolism, and protects cells from oxidative stress and inflammation." (PMID 37511397, 2023). "Different biological mechanisms are proposed to explain the adiposity-cancer link including altered sex hormone metabolism, increased insulin levels and the bioavailability of insulin-like growth factor 1 [IGF1], adipokine pathophysiology, and systemic inflammation." (PMID 37993940, 2023). "Since IGF-1 receptors have been found in a variety of human malignancies, insulin may have an influence on cancer cell proliferation in vivo." (PMID 36975729, 2023). "None of fasting glucose, insulin and glucagon showed significant associations with incident first cancer in the sensitivity analyses." (PMID 36611045, 2023). "Metformin may exert anti-cancer activity by decreasing the circulating estradiol, leptin, and insulin." (PMID 36562831, 2023). "Additionally, HK2 expression in cancers is stimulated by the insulin signaling pathway Akt/mTORC1, which is upregulated in tumor cells to regulate glucose metabolism, cellular growth, and survival through the phosphorylation of target molecules." (PMID 37109475, 2023). "In addition, FOXO can be regulated by insulin in cancer cells and thus participate in lipid metabolism." (PMID 37686221, 2023). "Since insulin/Akt signaling is strongly involved in cancer progression, KIAA1324-mediated regulation of insulin signaling may also suppress tumor development and invasion." (PMID 37612293, 2023). "Insulin has been shown to increase the growth of colon epithelial and carcinoma cells in vitro." (PMID 36819384, 2023). "Hence, our findings emphasize the importance of elevated fasting triglycerides combined with increase fasting insulin levels, as implemented by MCAi, on cancer prognosis." (PMID 35921366, 2022). "In addition, the insulin signaling pathway promotes cancer cell survival and proliferation via the RAS/RAF/MAPK kinase/ERK pathway." (PMID 35563777, 2022). "Previously, insulin was often regarded as an alternative factor of IGF-1 in cancer development." (PMID 35252207, 2022).
cancer (continued). "And the pancreatic islet inside PDA tissue will produce more insulin to nourish cancer cells." (PMID 35252207, 2022). "In particular, we show that the anti-cancer action triggered by metformin relies on its ability to inhibit the insulin/IR-mediated transduction pathway as well as the insulin-generated feedforward loop that couples CXCL12 induction by CAFs to CXCR4 expression by BCAHC‐1 cells." (PMID 35672854, 2022). "The KEGG pathway analysis focused on apoptosis, pathways in cancer, and insulin signaling pathway." (PMID 36199443, 2022). "Insulin and IGFs are potential players to cancer formation and progression, including RCC." (PMID 36314741, 2022). "In addition, KEGG pathway enrichment analysis indicated that the overlap DEGs were particularly involved in apoptosis, pathways in cancer, and insulin signaling pathway." (PMID 36199443, 2022). "Prior studies have reported that KD could reduce the energy supply and affect the proliferation and differentiation of cancer cells by lowering the blood glucose and insulin levels." (PMID 35600387, 2022). "A meta-analysis of the effect of insulin exposure as well as type of insulin (glargine vs. non-glargine insulin) showed that the risk of developing cancer is dependent on cancer type." (PMID 35158824, 2022). "In these cases, changing diet to improve insulin sensitivity would be predicted to have an effect on cancer and further reductions in weight may achieve additional antitumor effects as well." (PMID 36062923, 2022). "Next, to figure out whether this balance–imbalance is connected with the invasive ability of cancer cells, we induced Huh7 cells, another hepatoma carcinoma cell line but with high-invasive ability, to be resistant to insulin." (PMID 35873543, 2022). "Indeed, insulin deregulation is a common host adaptation to cancer growth, but cachexia significantly interests only a variety of cancer types." (PMID 36158184, 2022). "In addition, TXNIP has broad functions in energy metabolism, insulin sensitivity, and tumor suppressor activity in various cancer cells." (PMID 35429141, 2022). "Sex, statin use, insulin, cancer, AFB smear grade, and drug resistance." (PMID 36355885, 2022). "KEGG enrichment analyses showed that the 91 differential mRNAs dysregulated in PTE were mainly involved in metabolic pathways including GnRH development, cholinergic synapse, transcriptional misregulation in cancer, insulin secretion, the GnRH signaling pathway, and glutamatergic synapse." (PMID 36619916, 2022). "Concerning Metformin, many mechanisms of anti-cancer activity have been proposed, such as modulation of immunological and/or anti-inflammatory responses, inhibition of mTOR, and inhibition of the insulin signals and glucose synthesis via respiratory-chain complex I blockage." (PMID 36139522, 2022). "Insulin increases the secretion of growth-promoting substances such as IGF-1 (insulin like growth factor-1) causes higher growth of tumor and cancer cells, thus increasing the risk of cancer." (PMID 35685489, 2022). "Excess insulin is associated with an increased risk of cancer death that can be independent of obesity." (PMID 35189981, 2022). "Interestingly, some of these mechanisms, such as altered glucose metabolism and insulin signaling, have been studied in cancer etiology, whereas others such as dysregulated leptin signaling or thermogenesis have been investigated to a lesser extent." (PMID 36062923, 2022). "Insulin, stimulating mitosis and inhibiting apoptosis, promotes cancer growth." (PMID 35356420, 2022).
cancer (continued). "The importance of insulin signaling in preventing cancer cachexia was demonstrated by studies showing that mice bearing C26 tumors treated with rosiglitazone (insulin sensitizer), and patients treated with insulin itself, showed a reduction in cachexia markers." (PMID 35441960, 2022). "The insulin signaling pathway play an important role in the cancer cells growth and progression." (PMID 36199443, 2022). "It is hypothesized that a high insulin state can contribute to cancer growth through its mitogenic properties." (PMID 36422290, 2022). "Indeed, both in vitro and in vivo studies demonstrated that insulin and insulin receptor (IR) played a key role in cancer biology." (PMID 35222270, 2022). "Cancer cells can respond to the activating effects of insulin through signal transduction pathways." (PMID 36291064, 2022). "With close collaborations between academia and industry, recombinant IFNα2 became the first human immunotherapeutic approved by the US Food and Drug Administration (FDA) for cancer and, other than insulin, the first FDA-approved pharmaceutical product produced by recombinant DNA technology." (PMID 36091125, 2022). "The most significantly enriched pathways were apelin signaling pathway, sphingolipid metabolism, hippo signaling pathway, TGF-beta signaling pathway, insulin resistance, tight junction, cellular senescence, transcriptional misregulation in cancers, and lipid metabolism in the TG after TMD." (PMID 36051440, 2022). "In addition, insulin likely plays a role in malignant transformation, cancer development and metastasis of various cells by binding to and activating its structurally related IGF-1 receptor." (PMID 36714554, 2022). "Insulin/IGF signaling pathway is known to be activated in many cancers including HCC." (PMID 35568708, 2022). "Insulin is a well-known growth factor that increases cancer cell proliferation and, as a result, may have a role in carcinogenesis." (PMID 35145826, 2022). "A previous study showed that high levels of insulin or a followed-by increase in IGF‐1 may promote cancer growth." (PMID 36106112, 2022). "Some studies have suggested that decreased muscle function in cancer patients is the result of local muscle inflammation, and that increased inflammatory cytokines can also lead to insulin resistance and muscle depletion by activating the ubiquitin-proteasome proteolytic pathway." (PMID 35433784, 2022). "Studies that are adequately powered to evaluate whether insulin-lowering diets improve cancer outcomes are warranted." (PMID 36079800, 2022). "Most importantly, it was shown that excess insulin, a consequence of unhealthy diets and lifestyles, may promote inflammation and thereby have cancer-promoting effects." (PMID 34897573, 2022). "By activating the PI3K/Akt pathway, insulin stimulation may enhance cancer cell proliferation and inhibit apoptosis in vivo." (PMID 35923695, 2022). "Consequently, dysfunction in these pathways secondary to improper insulin signaling can lead to derangements in normal cell development and cancer." (PMID 35326592, 2022). "The CARING study, an observational study following 327,112 insulin users from five European countries, showed no consistent evidence in the cancer risk associated with insulin glargine or detemir use compared to human insulin use." (PMID 35681699, 2022). "As a result, insulin assists cancer cells to possess a relatively higher glucose up-taking efficiency than normal cells, which may help cancer cells gain advantages in survival competitions." (PMID 35252207, 2022). "Another metabolic adaptation that occurs in cancer cells involves the insulin signaling pathway." (PMID 36079800, 2022). "These elevated insulin values promote the activity of insulin growth such as factor 1 (IGF-1), which has been associated with an increase in cell proliferation as well as an inhibition in the apoptosis process, enhancing cancer development." (PMID 36145184, 2022).
cancer (continued). "Cancer cells exposed to insulin divide faster, leading to increased tumor growth." (PMID 35326592, 2022). "Furthermore, a high-fat diet promotes excess body adiposity, which can lead to cancer development by the mechanisms involved in elevated insulin and insulin-like growth factor 1 (IGF-1) secretion." (PMID 35406496, 2022). "In this way, preclinical studies of drugs that target IGF1 and/or insulin pathways suggest that modulating this pathway could find applications in cancer." (PMID 35406791, 2022). "Moreover, in cancer cells, glargine and long-acting insulins have been shown to exert a greater proliferative effect relative to human insulin both through the IGF1 receptor and IR isoform A." (PMID 35681699, 2022). "It is considered that the most likely mechanism that could explain the progression to cancer is a decrease in NK-cell activity and an abnormal inflammatory response due to an imbalance in insulin." (PMID 34174798, 2022). "MCFAs have been found to enhance immune response and insulin secretion and may increase apoptosis in cancer cells." (PMID 35885289, 2022). "However, GSEA identified several cancer-related signaling pathways including INSULIN, MTOR, and PPAR pathways that were enriched in the low-ADAMTS14 expression group." (PMID 35572505, 2022). "Thus, pancreatic islets regulate glucose metabolism and the growth of surrounding cancer cells—mediated predominantly through β-cell-derived insulin." (PMID 36142542, 2022). "Moreover, elevated HbA1c levels influences cancer progression through an increase in the levels of insulin, insulin-like growth factor-1 (IGF-1), and inflammatory cytokines in circulation." (PMID 35836264, 2022). "Existing evidence indicated that these foods containing high-glycemic carbohydrates and saturated and trans-fatty acids can lead to cancer development and tumor growth by the mechanisms involved in elevated insulin and IGF-1 secretion and proinflammatory status." (PMID 35406496, 2022). "But recently, more and more studies indicated that insulin might have an independent effect on cancer initiation and metabolic regulation." (PMID 35252207, 2022). "In addition to the insulin-mimetic effects of vanadium that have been well explored in clinical trials, investigations have also suggested direct anti-cancer effects of vanadium compounds through in vitro and in vivo experimentation." (PMID 35572196, 2022). "The biological mechanisms through which high PA and normal weight could prevent cancer are likely to be partially shared, for example, through improved immune function, modulated inflammation and enhanced insulin sensitivity." (PMID 35362551, 2022). "In addition to the observational evidence, many experimental studies provided solid confirmation of the positive relationship between insulin and cancer." (PMID 35933633, 2022). "An important limitation of the current study is that we did not use a transgenic mouse to evaluate the role of insulin, thyroid hormone, ion channel blockers, and cancer-associated microRNAs in RV performance." (PMID 36552341, 2022). "Cancer could use insulin to compensatorily activates multiple signal pathways to escape from IGF-1R inhibitors." (PMID 35252207, 2022). "HCV infection promotes IR through the insulin signaling pathway in hepatocytes and lead to a rise in levels of tumor necrosis factor and interleukin-6, which aid the advancement of liver steatosis and inflammation and subsequent cancer." (PMID 36115934, 2022). "Moreover, we characterize the translational targets of 4EBP1 and identify that 4EBP1 specifically regulates the translation of genes involved in insulin signaling, glucose metabolism, and the inositol pathway that plays a role in cancer progression." (PMID 35626002, 2022).